TOX (thymocyte selection associated high mobility group box)
Diseases named in the same sentence as TOX in open-access papers (continued):
Sharing a sentence is not in itself a finding about the gene and the disease.
tumor (continued). "Together, these findings suggest that TOX functions as an oncogenic factor and that AHR's tumor-suppressive role is, at least in part, mediated by repressing TOX expression." (PMID 40303305, 2025). "Remarkably, the expression of bona fide exhaustion-related transcription factors TOX- and IRF-4 was significantly less in aCEA-28ζ-sSF6 CAR T cells relative to control CAR T cells following three rounds of repetitive stimulation with tumor cells." (PMID 40558528, 2025). "Chronic antigen stimulation – Persistent viral or tumor antigens sustain TCR signaling, activating NFAT and inducing exhaustion genes (PD-1, TOX)." (PMID 41194917, 2025). "While in tumor‐core tissues, canonical CD8+T cells with GZMK/B/A and exhausted molecules (TOX and PDCD1) dominate, which is completely different from the naïve and low‐cytotoxic/exhausted states of CD8+T cells in the leading‐edge area." (PMID 39716897, 2024). "Tumour‐specific T cells in tdLNs express high levels of BCL6, which is correlated with T‐cell exhaustion, particularly TOX+ TCF‐1+ Tpex cells in both LNs and tumours." (PMID 39169517, 2024). "Compared to mice receiving vehicle‐treated T cells, tumor infiltrating T cells from mice receiving TAMo‐cocultured T cells exhibited higher levels of TCF‐1 and lower levels of TOX." (PMID 38386350, 2024). "TOX and TOX2 have been reported to induce tumor-specific T-cell exhaustion with upregulation of checkpoint proteins, such as TIM3 and PD-1." (PMID 39080376, 2024). "TOX and NR4A families of nuclear receptors were enriched in tumour-specific dysfunctional T cells and induced by chronic and constitutive stimulation of TCRs and activation of NFAT." (PMID 38581063, 2024). "Most PD-1+TCF1+ OT1 TILs during the tumor control phase after PD1d/IL-2v/IL-33 ACT expressed higher Gzmc and lower TOX protein relative to canonical TCF1+PD-1+ PEX-like cells from baseline tumors." (PMID 37081150, 2023). "Another study using a CAR T cell model demonstrated that TOX and TOX2 are necessary to impose CAR T exhaustion, which were highly induced in exhausted CAR+ tumor-infiltrating lymphocytes (CAR TILs)." (PMID 36761757, 2023). "Immunohistochemical staining targeted various T-cell markers (CD3, CD4, CD8, and FOXP3), T-cell exhaustion markers (TOX and TIGIT), a B-cell marker (CD20), and a neutrophil marker (CD66b) in tumor and tumor-free mucosa from both groups." (PMID 37835436, 2023). "Using a similar mouse model, NFAT was confirmed to induce expression of high-mobility group box (TOX/TOX2) and NR4A transcription factors in tumor-infiltrating, exhausted CD8+ PD1+ TIM3+ CAR-T cells." (PMID 37833991, 2023). "In studies on tumor-inoculated mice, it was shown that CAR-T cells deficient in both TOX and TOX2, or with triple KO of NR4A1, NR4A2, and NR4A3, had a greater anti-cancer activity and improved animal survival; therefore, targeting the TOX/NR4A axis may reduce the depletion of CAR-T cells in TME." (PMID 37296906, 2023). "Lastly, the loss of Arid2 promoted the expression of KLRD1 and inhibited TCF1 and TOX expression in the CXCR6+CD44+ cluster, further indicating an increased effector profile of tumor-specific CD8+ T cells following PBAF deletion." (PMID 37330910, 2023). "Here we showed that PTPN2/N1 inhibition reduces exhaustion and increases T cell memory signatures, as we observed reduced expression of PD-1, TOX and TIM-3 in chronically antigen-stimulated or tumour-infiltrating CD8+ T cells." (PMID 37794185, 2023). "Our study first described the expression of the exhaustion markers TOX and TIGIT in the mucosa and tumor of patients with CAC." (PMID 37835436, 2023). "We show that VEGF expression, for example, is enriched in the tumor parenchyma compared with the stroma; VEGF signaling has been found to promote PD-1, CTLA-4, TIM-3, and TOX expression on CD8+ T cells." (PMID 35584630, 2022). "Disruption the expression and activity of TOX and TOX2 in CAR T cells promoted tumor regression in tumor-bearing mouse models." (PMID 36568989, 2022).
tumor (continued). "The gene signatures of the TCM group include TOX, KIR3DL2 and GTSF1, which were previously reported in tumor-stage MF and Sézary syndrome." (PMID 35241665, 2022). "This study is the first to show a tumor-suppressive role for TOX in CRC and that TOX is more highly expressed in MSI CRC patients than MSS CRC patients." (PMID 33897695, 2021). "For example, VEGFA induces the expression of transcription factor TOX to drive T cell exhaustion, and the expression of CASP1 is able to be repressed by G9A and further promotes tumor immune escape." (PMID 34394098, 2021). "TOX and TOX2 induced T cell exhaustion in different tumor mouse models and cancer patients as well as in patient hematological malignancies." (PMID 33743809, 2021). "According to the data in TCGA tumor samples, the copy numbers of DHX37 were positively correlated with TIM3, LAG3 and NCOR2, while they were negatively correlated with PD-L1, RGS16 and TOX." (PMID 33490273, 2021). "When given prophylactically, anti-PD1 treatment led to an increase in the incidence of NASH–HCC and in the number and size of tumour nodules, which correlated with increased hepatic CD8+PD1+CXCR6+, TOX+, and TNF+ T cells." (PMID 33762733, 2021). "Regarding transcription factors, the two tumor-specific CD8+T subsets expressed comparable Eomes and TOX, while PD-1+CXCR5+CD8+T cells show higher T-bet and TCF7 expression." (PMID 34035252, 2021). "Most articles have reported the role of TOX in CD8+ T cells, but few have tested the function of TOX in tumor cells, especially in CRC." (PMID 33897695, 2021). "Together, these data suggest that TOX, and potentially TIM-3, CTLA-4, VISTA, TIGIT, KLRG1, TOX2, SIRT1, Ki-67, and Helios mRNA levels in CRC tumor tissues increase in advanced disease stages, suggesting their possible roles in CRC progression." (PMID 32393998, 2020). "We found that TOX and potentially TIM-3, CTLA-4, VISTA, TIGIT, KLRG1, TOX2, SIRT1, Ki-67, and Helios mRNA levels in tumor tissue were elevated in advanced disease stages, suggesting their potential roles in CRC progression." (PMID 32393998, 2020). "Scott found that TOX-deficient tumor-specific T cells failed to persist in cancers, and hypothesized that TOX-induced exhaustion serves as a negative feedback mechanism that prevents activation-induced T cell death and overstimulation of antigen-specific T cells." (PMID 32117960, 2020). "Because TOX is a transcription factor, we sought to examine expression of its known downstream targets, particularly RUNX3, a tumor suppressor gene frequently deleted or transcriptionally silenced in cancer." (PMID 31139323, 2019). "TOX is a transcription factor involved in CD4+ T-cell development with downstream effects on RUNX3, a known tumor suppressor gene." (PMID 31139323, 2019). "To test if TOX protein can be detected in the CD4+ T cells of MF lesions, we performed immunofluorescence (IF) staining on patch, plaque, and tumor MF biopsies, using benign chronic dermatitis (CD) lesions as the controls." (PMID 24947046, 2014). "High-dimensional flow cytometry of tumor-infiltrating T cells (TILs) revealed four clusters enriched for tumor-specific OT-I T cells expressing CD69 and PD-1, and differing in markers such as CD39, CD103, TCF1, TOX and TIM3." (PMID 41461987, 2026). "Early studies reported TOX to be a tumor-cell-specific marker of CTCLs including early MF; TOX was expressed in tumor cells of CTCLs but has not been detected in inflammatory cells of benign inflammatory dermatoses." (PMID 40361907, 2025). "Consequently, we constructed pseudobulk data to decipher the relationships among IL-2 response states, STAT5 activation in Tregs, and TOX expression in CD8+ effector and tissue-resident T cells within tumor samples." (PMID 40698080, 2025).
tumor (continued). "CRISPR screens have discovered that TOX can promote CD8 + T cell exhaustion in collaboration with NR4A, and TOX serves as a significant downstream regulatory molecule reversing tumour-infiltrating T cell exhaustion with BATF and IRF4, which were the hits in several CRISPR screenings." (PMID 38581063, 2024). "Absence of TOX results in the loss of the TSL population and loss over time in their effector progeny in chronic infection and tumor models." (PMID 39211052, 2024). "ITK inhibition did not change the expression of TCF1 and TOX in tumor specific CD8 + T cells in tumors, while anti-PD-1 treatment decreased TCF1 expression." (PMID 37735204, 2023). "Consistent with our epigenetic and transcriptional profiling data, CD8+ T cells from AC484-treated tumours had lower TIM-3 and TOX expression and an overall reduction in the frequency of TIM-3+ TOX+ cells compared with untreated mice and anti-PD-1-treated mice." (PMID 37794185, 2023). "While TOX is transiently expressed in non-exhausted CD8 T cells after activation, TOX expression in our tumor samples correlated with poor IFN-γ production and therefore exhaustion (data not shown)." (PMID 38187391, 2023). "The results suggest that the expression of TOX does not appear to be enormously increased in CAC (mucosa or tumor) compared to sCRC, in contrast to recent interesting observations of increased numbers of exhausted CD8+ T-cells in the context of IBD." (PMID 37835436, 2023). "Simultaneous loss of TOX and TOX2 improves the antitumor potency of TILs, but loss of TOX2 alone is not sufficient to significantly reduce tumor burden, suggesting that, in mouse models, the contribution of TOX2 to exhaustion is weaker compared to TOX." (PMID 37467321, 2023). "CTCL cells are CD4+CD8-, wherein TOX is overexpressed, but TOX expression is not tumor-specific as other phenotypes of CTCL cells, including CD4+CD8+ and CD4-CD8-, also express TOX." (PMID 36969216, 2023). "Even when patients were stratified in quartiles depending on SMG1 expression in tumor samples, those with lower tumor levels of SMG1 displayed a CD8 phenotype with more abundance of cells expressing exhaustion markers (LAG3, PD-1, CTLA-4, TIM3, TOX)." (PMID 36443756, 2022). "Importantly, some of these experimentally validated bystander cells had a transcriptional phenotype similar to tumor-specific progenitor PD-1+ CD8+ T cells characterized in other studies, marked by expression of IL7R (CD127), TOX, and TCF7 (TCF-1)." (PMID 35584630, 2022). "The increased expression of the exhaustion markers PD-1, Eomes, and TOX on tumor-infiltrating CD8+ T cells in mice lacking intratumoral IL-33 production by skin-derived Cxcl13-Cre+ FSCs is consistent with the phenotype of terminally exhausted T cells." (PMID 34354077, 2021). "The density of tumor-infiltrating non-malignant TOX−CD4+ T cells surrounding their malignant TOX+ counterparts increased by 68% in tumors compared to plaques (median 453 cells/mm2 vs. 269 cells/mm2, p < 0.0001)." (PMID 34885092, 2021). "Because TOX may inhibit EMT and TOX expression decreases with increasing AJCC stage, we also delivered engineered cancer cells by tail vein injection to test the influence of TOX on tumor metastasis." (PMID 33897695, 2021). "Our in vivo experiments provide further support for the tumor-suppressive role of TOX, where TOX overexpression inhibited tumor formation of SW1116 cells and lung metastasis of MC38 cells, and rapamycin significantly attenuated tumor progression of shTox MC38 cell-injected mice." (PMID 33897695, 2021). "TOX expression was positively correlated with the expression of various IC molecules, such as PD-1, TIM-3, and TIGIT—at protein level—in the TI CD8+ T cells isolated from both NSCLC and HNSCC tumor tissues." (PMID 32111241, 2020). "Stable knockdown of TOX in CTCL cells has promoted apoptosis and reduced cell cycle progression, leading to less cell viability and colony-forming ability in vitro and reducing tumor growth in vivo." (PMID 31676945, 2020).
tumor (continued). "Stable knockdown of TOX in CTCL cells reduces cell cycle progression and promotes apoptosis, leading to inhibited cell viability and colony-forming ability in vitro and suppressed tumor growth in vivo." (PMID 31676945, 2020). "Levels of TIM-3, CTLA-4, TIGIT, TOX, TOX2, and SIRT1 genes in tumor tissue were significantly higher than that of the circulation; their expressions within the TME could be induced by tumor-mediated immunosuppression." (PMID 32393998, 2020). "Three of those genes, PCNA, ATP5C1, and NUSAP1, were confirmed to be co-expressed with TOX in tumour samples, but not in normal skin and atopic dermatitis, and as a result, they have a potential to be a diagnostic marker in CTCL." (PMID 32751918, 2020). "TOX together with other classical immune checkpoints including PD1 and CD270 are closely related to the development of several immune-relevant cell subsets which affect tumor progression." (PMID 32762688, 2020). "According to previous studies, TOX plays an important role in the development of thymus CD4+ T cells, NK cells, and intrinsic lymphocytes and is critical in the differentiation of tumor-specific T cells." (PMID 33299644, 2020). "By this means, recently published data showed that downregulation of key proteins involved in T cells terminal differentiation and exhaustion such as NR4A, TOX/TOX2, TET2, Regnase1, or PTPN22 increased T cell-based treatment half-life and improve anti-tumor performance." (PMID 33287392, 2020). "However, TOX overexpression in CD8+ tumor-infiltrating lymphocytes was also related with tumor immunosuppressive microenvironment, T cell exhaustion, and tumor persistence." (PMID 31817155, 2019). "Moreover, immunofluorescence co‐localization analysis of patient‐derived CRC tumour sections revealed a significant spatial correlation (Pearson's r > .6) between TNFRSF18 and the canonical CD8+ T cell exhaustion marker TOX,43, 44, 45 exclusively within the tumour microenvironment." (PMID 40770837, 2025). "Moreover, CD8+TILs from mice with HPD demonstrated impaired function and high TOX expression, and TIM-3 and PD-1 co-blockades could enhance the anti-tumor immunity of CD8+TILs." (PMID 41315319, 2025). "Tumour-infiltrating CD8+ T cells displayed high expression of exhaustion and activation markers PD-1 (91.0% ± 12.1), CD39 (56.4% ± 22.8) and HLA-DR (53.9% ± 22.4), low levels of TCF1 (5.6% ± 5.0), while a fraction of tumour-infiltrating CD8+ T cells expressed TOX (21.7% ± 14.81)." (PMID 38986249, 2024). "During the later phase of tumor growth (days 11–14), CD44hiCD62loTcf1–CD8+ TILs in WT mice gradually gained expression of immune checkpoint molecules (PD-1, Tim3, Lag3, Ctla4) and TOX, a master transcription factor responsible for reprograming CD8+ T cells into the exhausted state." (PMID 38787791, 2024). "Among the rich screen results, several intriguing genes (BATF, PRDM1, and TOX) and signalling cascades (JAK-STAT and NF-κB pathways) have been identified to extensively engage in multiple branches of T cell anti-tumour responses and might be leveraged to advance cancer immunotherapies." (PMID 38581063, 2024). "Analysis of tumour-infiltrating lymphocytes revealed no changes in the expression of memory-associated markers (CD62L and CD44) or exhaustion-associated markers (TIM3, PD1, LAG3, TOX) in CD4+ or CD8+ cells." (PMID 37605057, 2023). "Importantly, the expression of TOX, TOX2 and members of the NR4A family was highly induced in CD8+CAR+PD-1hi1TIM3+hi tumor-infiltrating lymphocytes (TILs) by the Cl/Cn-regulated nuclear factor of activated T cells (NFAT), even in the absence of activating protein-1, which is its partner protein." (PMID 36969216, 2023). "Furthermore, deletion of TOX in the T cells disabled the original depletion program, as tumor-specific T cells lacking TOX no longer upregulated genes for inhibitory receptors." (PMID 38026944, 2023).
tumor (continued). "These genes were defined as the tumor reactive signature (TRS), including co-inhibitory receptors (CTLA4, PDCD1, TIGIT and HAVCR2), reactive markers (CD38 and ENTPD1), effector molecules (NKG7 and PRF1), tumor necrosis factor TNFRSF9 and critical exhaustion-related regulator TOX." (PMID 34804045, 2021). "In addition, we investigated that the expression of DHX37 was correlated with several tumor-related immune genes (PD-L1, TIM3, LAG3, TOX, RGS16, and NCOR2), indicating that it may play crucial roles in tumor immune dysregulation." (PMID 33490273, 2021). "However, other studies have shown that depletion of TOX and TOX2 in tumor-specific T-cells leads to decreased persistence, suggesting that the biological relevance of TOX may extend beyond merely promoting the exhausted phenotype." (PMID 34639168, 2021). "This may suggest that elevated expression of PD-1, TIM-3, CTLA-4, TIGIT, TOX, TOX2, and SIRT1 genes in the TME of CRC is induced by tumor-associated, factors, unlike VISTA, and LAG-3." (PMID 32393998, 2020). "It was demonstrated that TOX and TOX2 can cooperatively work together to induce T cell exhaustion by upregulating IC expression in chimeric antigen receptor (CAR) T cell model, and their targeting was shown to be beneficial in enhancing anti-tumor immune responses and reducing tumor growth." (PMID 32393998, 2020). "Therefore, TOX plays critical but different role on the development of normal immunity and the regulation of tumor microenvironment, which is needed for identification in specific stage." (PMID 32700817, 2020). "However, few patients harboured SVs in TOX and WWOX, indicating these genes may rarely act as tumour suppressor genes in DLBCL." (PMID 30275490, 2018). "Furthermore, we identified a proliferative human CD8+ T cell subset in tumour-bearing HIS mice that expressed activation and exhaustion markers including very high levels of PD-1 and CD39 while having low expression of the progenitor marker TCF1 but high expression of TOX." (PMID 38986249, 2024). "Notably, and contrary to previous reports, we found that the expression of both granzyme B and Ki67 was almost exclusively limited to TOX+CD8+ T cells, demonstrating that these cells, despite showing high expression of PD-1 and TOX, are not functionally exhausted in this tumour model." (PMID 35508656, 2022). "Moreover, based on the finding that TOX expression was negatively correlated with the effects of PD-1 immunotherapy, it has been speculated that combined anti-TOX or anti-TOX2 and immune checkpoint inhibitor therapy may be a new approach for tumor immunotherapy." (PMID 33743809, 2021). "Furthermore, they presented more proof that tumor-specific T-cell exhaustion is driven by a prolonged encounter with tumor-specific antigen as tumor non-specific Tc did not express a high level of TOX gene and remained functional, unlike the tumor-specific TCRtag cells." (PMID 32823814, 2020). "TOX expression has been analyzed in cutaneous T-cell lymphomas (CTCL) and noticed that its expression is not tumor-specific or restricted to CD4+ CD8- phenotype." (PMID 36741360, 2022). "Notably, this study identifies TOX as an oncogenic factor in non-immunological contexts and underscores AHR's tumor-suppressive function through TOX repression, offering novel insights into the mechanisms underlying As3+-induced carcinogenesis." (PMID 40303305, 2025). "However, TOX, LMCD1, and AFAP1L2 were either not detected or only at very low levels, suggesting that their presence in tumor-infiltrating T cells was not a consequence of the canonical T cell activation program." (PMID 37388918, 2023). "It is noteworthy that once TOX is knocked out, CD8SP lymphocytes can differentiate into normal effector and memory cells under conditions of acute infection, while they do not persist in the tumor microenvironment." (PMID 36969216, 2023).
tumor (continued). "Furthermore, the TOX expression in CD8+ effector T cells was induced by Treg-mediated IL-2/STAT5 activation, while CD8+ tissue-resident T cells showed no corresponding changes in tumor samples." (PMID 40698080, 2025).